ERBB2 (erb-b2 receptor tyrosine kinase 2)
Diseases named in the same sentence as ERBB2 in open-access papers (continued):
Sharing a sentence is not in itself a finding about the gene and the disease.
pancreatic cancer (continued). "Collectively, specific activation or forced overexpression of either ErbB2 or ErbB3 attenuates VPA-induced apoptosis and inhibition of cell proliferation/survival in pancreatic cancer cells via constitutive activation of downstream Akt and MAPK signaling pathways." (PMID 30961642, 2019). "In consideration of this, VPA may be an excellent candidate drug against pancreatic cancer with a strong activity of triple-targeting EGFR, ErbB2, and ErbB3." (PMID 30961642, 2019). "To investigate the molecular mechanism by which VPA down-regulated EGFR, ErbB2, and ErbB3 in pancreatic cancer cells, we next explored whether treatment with VPA might modulate EGFR, ErbB2, and ErbB3 mRNA levels." (PMID 30961642, 2019). "The ERBB2 gene is also overexpressed in other cancers such as prostate, colon and pancreas cancers, and this alteration has also been considered as a negative prognosis marker by some authors." (PMID 12942124, 2003). "The network analysis revealed a positive link between ERBB2 and PPP3CB, which suggested that PPP3CB might inhibit pancreatic cancer through the ERBB pathway, because the ERBB family are overexpressed in pancreatic cancer and play key roles in its carcinogenesis." (PMID 33270085, 2021). "To explore whether VPA might show any therapeutic effect on pancreatic cancer, we investigated its anti-proliferative/anti-survival activities in the EGFR/ErbB2/ErbB3-coexpressing (HPAF-II, MPanc96) and ErbB3-negative (MiaPaca-2, Panc-1) pancreatic cancer cell lines." (PMID 30961642, 2019). "We show that human MUC4 and ErbB2 do physically interact in pancreatic cancer cells and that inhibition of expression of each membrane partners does not impair the same signalling pathways (inhibition of MUC4 expression affects the JNK pathway whereas that of ErbB2 alters the MAPK pathway)." (PMID 22393391, 2012).
bladder cancer (281 papers, 2003 to 2026). "The most common ERBB2 oncogenic variant in bladder cancer and one of the most common ERBB2 oncogenic variants overall." (PMID 40770324, 2025). "To excavate the cause of the expression alterations of ERBB2 in luminal and basal bladder cancer, we first focused on CNV and somatic mutations." (PMID 39840049, 2024). "An exome study of shed DNA from dogs with suspected bladder cancer also found the nearby ERBB2 mutation, G292R20 which was observed in one of our transcript sequences." (PMID 38778091, 2024). "CSTF2 has previously been implicated as a promoter of lung and bladder cancer, through the regulation of ERBB2 and RAC1 3′ UTRs, respectively." (PMID 32029502, 2020). "It has been shown that AR can increase expression and activity of EGFR and a protein encoded by the ERBB2 (also known as Her2) gene, implying androgen-mediated bladder cancer tumorigenesis and clinical progression via the regulation of the EGFR/ERBB2 pathways." (PMID 26347776, 2015). "A number of studies have reported the association of EGFR and ErbB2 overexpression with advanced stages of bladder cancer." (PMID 22991510, 2012). "Overexpression of ErbB2 and/or NFκB was also identified as an independent risk factor for bladder cancer death with marginal statistical significance (P = 0.056)." (PMID 22102915, 2011). "ERBB2 has been reported to be highly enriched in bladder cancer and associated with poor clinical outcomes, suggesting that it might be a promising therapeutic target." (PMID 39840049, 2024). "In addition, it has been proved that the mutation of ERBB2 also affects the proliferation and signaling pathways of bladder cancer cells." (PMID 38678587, 2024). "We observed frequent CNV and mutations of ERBB2 in bladder cancer." (PMID 39840049, 2024). "Overexpression of ErbB2 was seen in bladder cancer and is associated with poor prognosis." (PMID 35990198, 2022). "ERBB2 mutations are known to be present in bladder cancer and could be potentially used for precision medicine purposes." (PMID 33946229, 2021). "ERBB2 mRNA is associated with luminal subtypes of bladder cancer." (PMID 33050010, 2020). "In addition to the PIK3CA mutations, we found signatures 2 and 13 to be associated with ERBB2 p.S310F (c.929C>T) mutation in bladder cancer, and signature 13 to be associated with PPP2R1A p.P179R (c.536C>G) mutation in uterine corpus endometrial carcinoma." (PMID 30412573, 2018). "Notably, we report novel associations between APOBEC activity and ERBB2 S310F mutations in bladder cancer." (PMID 29748584, 2018). "Through multivariate analysis, overexpression of erbB2 and/or NFκB was identified as an independent risk factor for bladder cancer death with marginal significance (hazard ratio 21.5, P = 0.056) along with chemoradiation resistance (P = 0.003) and hydronephrosis (P = 0.018)." (PMID 22102915, 2011). "For example, GEC showed an especially high proportion of predicted subclonal ERBB2 mutations across domains (25.2% ECD, 42.9% TMD, 26.0% KD, and 29.8% other) and a sizable proportion of ECD mutations in bladder cancer (23.8%) also seemed to be subclonal." (PMID 40178042, 2025). "The receptor tyrosine kinase ERBB2 was primarily amplified in bladder cancer, while FGFR4 and EGFL7 alterations were mainly seen among RCC cases." (PMID 38398121, 2024). "In summary, ERBB2 was highly enriched in luminal bladder cancer and expressed at lower levels in basal bladder cancer." (PMID 39840049, 2024). "Overall, these results indicated that RC48’s efficacy against bladder cancer cells depends on ERBB2 expression." (PMID 39840049, 2024). "Using large-scale mRNA expression profile datasets, Western blotting, and immunohistochemistry, we first found that ERBB2 is upregulated in the luminal type but downregulated in basal bladder cancer." (PMID 39840049, 2024). "Our study found that ERBB2 expression was higher in luminal bladder cancer and negatively correlated with basal bladder cancer." (PMID 39840049, 2024).
bladder cancer (continued). "In summary, the copy number variant of ERBB2 was more frequent and had a greater influence on ERBB2 mRNA expression levels in luminal bladder cancer compared to basal bladder cancer." (PMID 39840049, 2024). "We found that the chromosomal locus containing ERBB2 exhibited a lower G-score in basal bladder cancer and a higher G-score in luminal bladder cancer." (PMID 39840049, 2024). "Nevertheless, evidence suggests that ERBB2 exhibits different levels of enrichment across different bladder cancer subtypes." (PMID 39840049, 2024). "In this current investigation we examined RAD21, RAD50 or/and BARD1 co-expression with different status of ERBB2 expression and assessed their prognostic and clinical significance in bladder cancer." (PMID 37474724, 2023). "This instigates the importance of further assessing HER2/ERBB2 in the context of bladder cancer from different angles." (PMID 37474724, 2023). "Both the mRNA and protein expression of SATB1 and ERBB2 were significantly upregulated in bladder cancer tissues when compared to normal bladder tissues." (PMID 37627900, 2023). "With this emerging data, HER2-targeted therapies are being tested in patients with bladder cancer harboring HER2 overexpression and/or amplification of ERBB2." (PMID 38136267, 2023). "The most frequently mutated genes in ordinary bladder cancer are TP53x, KMT2A, SPTAN1, ERBB2, CREBBP, FAT1, ATM, and KMT2C." (PMID 36779496, 2023). "This study evaluates the biological and prognostic significance of RAD21, RAD50 and BARD1 (homologous recombination biomarkers) mRNA levels with ERBB2 low and high expression to explore their impact on bladder cancer patient survival and cancer aggressiveness." (PMID 37474724, 2023). "We recently highlighted the interplay between ATM (one of the homologous recombination factors) and ERBB2 in bladder cancer patients." (PMID 37474724, 2023). "In the current study, we observed a significant overexpression of ERBB2 in bladder cancer tissues compared to normal." (PMID 37474724, 2023). "Published data reported amplification of the ERBB2 gene in up to 42% and up‐regulation of protein expression in up to 30% of bladder cancer cases." (PMID 36056635, 2022). "The expression patterns of ATM/ERBB2 mRNAs were also investigated at the protein level in the TCGA‐bladder cancer cohort." (PMID 36056635, 2022). "In this cohort (Cohort three), 10 normal bladder mucosae samples, 58 normal looking bladder mucosae surrounding cancer and 165 primary bladder cancer samples were profiled for ERBB2 and ATM mRNA expression using Illumina human‐6 v2.0 expression beadchip." (PMID 36056635, 2022). "For example, EMP3 overexpression and knockdown in human bladder cancer cells have been shown to culminate into a concomitant increase and reduction in ErbB2/HER2 protein levels, respectively." (PMID 34067658, 2021). "Accordingly, HER2-targeted therapies need to be tested in patients with bladder cancer harboring HER2 overexpression, and/or amplifications or other mutations of ERBB2 which encodes HER2." (PMID 35004854, 2021). "Promotion: Studies show that ARs increase the protein level and activity of the epidermal growth factor receptor (EGFR) as well as Herb2, promoting the development and progression of bladder cancer through the EGFR / ERBB2 pathway." (PMID 33919565, 2021). "Overexpression of EGFR, ERBB2 or ERBB3 is associated with tumor grade, stage, and prognosis in bladder cancer." (PMID 34094968, 2021). "Next, EGFR and ERBB2/HER2 protein expression was evaluated in a large cohort of bladder cancers with substantial squamous differentiation comprising MIX-SCC (n = 50) and pure SCC (n = 75)." (PMID 32978523, 2020).
bladder cancer (continued). "ERBB2 amplification was also common in bladder cancer and UTUC (6.2%: 64 of 1032 bladder tumors and 4.4% of UTUC: 9 of 204 tumors)." (PMID 32332851, 2020). "ERBB2 belongs to the key bladder cancer genes as recently defined in an international consensus paper." (PMID 33050010, 2020). "Gene expression differences among NMIBCs have been reported previously, and pathways relevant to tumor biology in bladder cancer are ERBB2, PI3K-AKT, cell cycle, MAPK, and DNA-damage repair." (PMID 32670866, 2020). "We have recently shown that AR signals increase EGFR and ERBB2 expression and activity, suggesting androgen-mediated bladder cancer progression via the regulation of the EGFR/ERBB2 pathways." (PMID 22922989, 2012). "Data on ERBB2 immunohistochemistry in bladder cancer are plentiful and a variety of antibodies, methods and scoring techniques have been used." (PMID 21364580, 2011). "Pathway analysis of affymetrix data file shows upregulation of four genes ERBB2, DAPK1, FGFR3 and CDKN2A which have reference to prove their involvement in causing bladder cancer." (PMID 22276047, 2011). "Indeed, EGFR on chromosome 7 and ERBB2 on chromosome 17 have been reported to promote bladder cancer development." (PMID 41139203, 2025). "Mutations in PIK3CA, FGFR3, and ERBB2 highlight the relevance of the receptor tyrosine kinase (RTK)–RAS–PI3K signaling cascade in urothelial cancer pathogenesis, in line with previous studies documenting PI3K pathway alterations in 20–30% of bladder cancers." (PMID 41373802, 2025). "Consistent with this, ERBB2 expression mediates the sensitivity of bladder cancer cells to RC48." (PMID 39840049, 2024). "Additionally, the most frequently mutated genes in ordinary bladder cancer are KMT2C, ATM, FAT1, CREBBP, ERBB2, SPTAN1, and KMT2A." (PMID 39399176, 2024). "To further determine whether the JAK/STAT3 pathway occurred as a compensatory activation based on the downregulation of ERBB2 in basal bladder cancer, we performed RNA-sequencing to explore this speculation." (PMID 39840049, 2024). "Due to the heterogeneous expression and epigenetic alterations of ERBB2 in luminal and basal bladder cancer, we speculated that these two subtypes might exhibit different sensitivities to RC48." (PMID 39840049, 2024). "We found that ERBB2 was highly expressed in luminal bladder cancer (p-value < 0.01)." (PMID 39840049, 2024). "RC48 is an ADC targeting ERBB2 and has been reported as a promising therapeutic method for treating various cancers, including breast cancer, gastric cancer, non-small-cell lung cancer, and bladder cancer." (PMID 39840049, 2024). "Also, the exact molecular mechanism between our homologous recombination targets and ERBB2 still need to be investigated to improve prognosis and treatment efficacy in bladder cancer." (PMID 37474724, 2023). "Importantly, here we showed that high RAD21, RAD50 or BARD1 mRNA expression in bladder cancer patients with low-ERBB2 exhibit poor survival." (PMID 37474724, 2023). "The effectiveness of Lapatinib and Sunitinib in bladder cancer may be related to their inhibition of ErbB1 or ErbB2 tyrosine kinase activity." (PMID 37152941, 2023). "Importantly, it provided novel findings and potential prognostic markers, particularly in ERBB2-low bladder cancer." (PMID 37474724, 2023).
bladder cancer (continued). "Studies have shown the potential prognostic value of markers including receptor tyrosine kinases such as fibroblast growth factor receptor 3 (FGFR3), epidermal growth factor receptor (EGFR), and ERBB2/human epidermal growth factor receptor 2 (HER2) in invasive bladder cancers." (PMID 33312739, 2020). "Notably, a biomarker-driven clinical trial was conducted to overcome chemoradiation resistance of erbB2-overexpressing bladder cancer." (PMID 30223570, 2018). "Recently, the use of improved AdnaTest immune-magnetic systems also allowed the identification of CTC with stem-like features by PCR-based methods, showing that ALDH1 mainly contributed to CTC positivity compared to EPCAM, MUC1, or ERBB2 in bladder cancer patients." (PMID 28321147, 2017). "A factor contributing to the disparate results is most likely the underlying heterogeneity of bladder cancer and the lack of adequate molecular descriptions of bladder cancer molecular subtypes; the context in which the ERBB2 and EGFR targets operate." (PMID 28388586, 2017). "Gene amplification is one of the mechanisms underlying the activation of proto-oncogenes such as ERBB2, CCND1, CCNE1, MDM2, and E2F3, which have been suggested as cancer driver genes in bladder cancers, based on their aberrant gene amplification and protein overexpression." (PMID 27902773, 2016). "Additionally, it has been found that dihydrotestosterone upregulates ERBB2 in androgen receptor positive bladder cancer cells." (PMID 26347776, 2015). "Furthermore, the oncogenes NRAS and ERBB2 are up-regulated in bladder cancer, hypothetically, due to lower of expression of miR-28-5p and miR-125b, respectively." (PMID 23717626, 2013). "We have recently shown that AR activation results in upregulation of EGFR and ERBB2 expression in bladder cancer cells, which may play an important role in androgen-mediated tumor progression." (PMID 22922989, 2012). "Indeed, we have confirmed that low-dose Hsp90 inhibitors effectually potentiate the effects of CRT on bladder cancer cells overexpressing erbB2 and NFκB in preclinical models." (PMID 22102915, 2011). "In addition, we observed an upregulation of ERBB2 linear copy number in luminal bladder cancer." (PMID 39840049, 2024). "Furthermore, ERBB2 silencing resulted in lower gDS in luminal bladder cancer." (PMID 39840049, 2024). "Moreover, we observed a higher rate of ERBB2 amplification in luminal bladder cancer." (PMID 39840049, 2024). "However, given that ERBB2 overexpression is associated with disease progression in bladder cancer, supplementing ERBB2 expression to treat basal bladder cancer is clearly not a viable approach." (PMID 39840049, 2024). "Therefore, we speculated that basal bladder cancer exhibits lower ERBB2 expression and is less sensitive to RC48." (PMID 39840049, 2024). "Altogether, a strong overlap of ERBB2-driven pathways was found with our homologous recombination factors, which may help define a signature to select bladder cancer patients who may benefit from targeted therapy and may use to evaluate drug response for patients." (PMID 37474724, 2023). "Finally, high-grade bladder cancer that over-expresses ErbB2 might be treatable with trastuzumab, a drug targeting ErbB2 in BC." (PMID 25029196, 2014). "The results showed that compared with normal tissues, ESR1, PTGS2 and BCL2 in bladder cancer tissues were significantly down-regulated; CASP3, INS, SRC, CDK4, GSK3B and ERBB2 were significantly up-regulated." (PMID 41287122, 2025). "In five bladder cancer datasets (TCGA-MIBC, GSE13507, GSE48075, GSE32894, and GSE48276), ERBB2 was highly positively correlated with GATA3 and FOXA1 but negatively correlated with CD44 and KRT5, suggesting that ERBB2 is a luminal marker to some extent." (PMID 39840049, 2024). "The expression of ERBB2, RAD21, RAD50 and BARD1 mRNA levels was assessed in The Cancer Genome Atlas (TCGA) bladder cancer dataset along with four validation cohorts." (PMID 37474724, 2023).